ACE (angiotensin I converting enzyme)
Diseases named in the same sentence as ACE in open-access papers (continued):
Sharing a sentence is not in itself a finding about the gene and the disease.
cardiovascular disease (continued). "The presence of cardiovascular diseases in patients that are under β-blockers and ACE-inhibitors is a confounding factor for side-effects during AIT, so large prospective observational studies on the safety of these medicines, taking under consideration the underlying diseases, are needed." (PMID 31528333, 2019). "Agents acting in this system primarily operate for cardiovascular disease, and belong to the three main drug classes of 1) angiotensin-converting enzyme (ACE) inhibitors; angiotensin II receptor blockers (ARBs, sartans); and direct renin inhibitors, such as aliskiren." (PMID 30744022, 2019). "However, different studies on the ACE DD genotype effect on cardiovascular diseases have produced different results." (PMID 30231548, 2018). "Furthermore, the leaves of Coriandrum sativum as a source of important therapeutical flavonoids particularly with ACE inhibition mechanism to combat with various cardiovascular diseases were explored for the first time in this study." (PMID 30581531, 2018). "In 2001, Professor Richard Peto and others first outlined the concept of using the fixed-dose combination of aspirin, a statin, an angiotensin-converting enzyme (ACE) inhibitor, and a beta blocker for cardiovascular disease secondary prevention in low- and middle-income countries." (PMID 26263422, 2015). "Therefore, ACE inhibitors have been widely considered to prevent angiotensin II production in cardiovascular diseases, and utilized in clinical applications since the discovery of ACE inhibitors in snake venom." (PMID 25295218, 2014). "One of the causes of individual differences in effectiveness of AT1 receptors blockers and ACE inhibitors in the cardiovascular diseases might result from different role of these compounds in the regulation of cardiovascular reactions to stress." (PMID 25045668, 2014). "An effort was also made to correlate the soluble ACE levels to cardiovascular disease." (PMID 24691269, 2014). "Our data suggest that ACE activity is suppressed by the endogenous inhibitor, which may provide a protective mechanism for cardiovascular disease." (PMID 24691160, 2014). "ACE inhibitors remain an effective therapeutic strategy in the treatment of cardiovascular disease." (PMID 24015848, 2014). "Some other mutations of the ACE gene are known to be coupled with a mildly elevated ACE concentration, but again without an enhanced incidence of cardiovascular diseases." (PMID 24690767, 2014). "Several studies have suggested that the major components of the RAS, ACE and Ang II, possess considerable effects in cardiovascular disease processes and might be modulated by some components of gene abnormalities and disorders." (PMID 25984491, 2014). "The aim of this study is to assess the association of two polymorphisms, the cartilageintermediate layer protein 2 (CILP2) G/T and angiotensin convertingenzyme (ACE) I/D, with blood pressure and anthropometrical andbiochemical parameters related to the development of cardiovascular disease." (PMID 24350279, 2013). "Present analysis showed that the Bayash Roma of Croatia, in comparison with other European populations, do not carry an increased genetic risk for cardiovascular diseases related to the most common polymorphisms of the ACE, eNOS and LEP genes." (PMID 23390466, 2012). "Among those with at least one ACE I allele, individuals with the BDKRB2 C181T TT or BDKRB2 C181T CT genotypes had a significantly higher hazard of cardiovascular disease as compared to those who carried the BDKRB2 C181T CC genotype (adjusted HR = 1.77, 95% CI: 1.20–2.61)." (PMID 20856803, 2010). "DOTA-LIS-02 emerged as the most promising candidate among the different lisinopril-based conjugates, which could be useful for imaging physiological levels of ACE in cardiovascular disease and Covid-19 after labeling with PET radiometals such as gallium-68 or scandium-44." (PMID 40481263, 2025).
cardiovascular disease (continued). "Our data suggest, but do not prove, that the lower use of ACE inhibitors in group H could be related to the increased risk of cardiovascular disease, although this relationship is uncertain." (PMID 38481445, 2024). "They allowed evaluating salmon and carp proteins as potential sources of ACE-inhibiting and antioxidant peptides and characterizing products of their in silico simulation of human-like gastrointestinal digestion regarding their applicability in the prevention of cardiovascular diseases." (PMID 34375367, 2021). "Therefore, ACE is a key drug target for the treatment of cardiovascular system diseases." (PMID 30998765, 2019). "They proposed that this polypill comprising of six drugs (aspirin, statin, beta-blocker, angiotensin converting enzyme (ACE) inhibitor, diuretic and folic acid) could reduce burden of cardiovascular disease (CVD) by 80% when taken by all above the age of 55 years and those with CVD." (PMID 28425033, 2017). "Therefore it is not surprising that association of ACE DD genotype with cardiovascular disease was not strong, in a sharp contrast to ACE phenotype." (PMID 24691160, 2014). "The beta-blocker would be better replaced by a calcium channel blocker and/or ACE inhibitor, both of which have greater population heath benefits for a similar level of cost-effectiveness, and recent evidence has cast doubt on the benefits of aspirin in primary prevention of cardiovascular disease." (PMID 22657090, 2012). "Peptides obtained from the mung bean protein hydrolysate act as an angiotensin I-converting enzyme (ACE) inhibitor with an IC50 value of 0.64 mg protein/mL, which can be used for the prevention of cardiovascular disease." (PMID 38998943, 2024). "Their capability of inhibiting angiotensin-converting enzyme (ACE), makes TML a functional food useful for the prevention of cardiovascular diseases." (PMID 39517234, 2024). "The results also revealed angiotensin-converting enzyme (ACE)-inhibitory activity, which indicated the potential of GSE to deal with cardiovascular disease events." (PMID 38231829, 2023). "Because cardiovascular disease is more important than the comparatively rare systemic allergic sting reactions, appropriate management of cardiac disease is a priority, even though β-blockers or ACE inhibitors may adversely affect the course of an anaphylactic reaction." (PMID 37854067, 2023). "The increased plasma ACE level may result in an increase in the expression levels of interleukin-6 (IL-6) and kallikrein (KLK1), which subsequently increases coronary plaque vulnerability, ulceration, and thrombosis, leading to an increased risk and mortality of cardiovascular diseases." (PMID 35885904, 2022). "The purpose of the study was to investigate the role in cardiovascular disease (CVD) of PAI-1, ACE, ApoB-100, MTHFR A1298C, and C677T." (PMID 35330428, 2022). "This blockbuster angiotensin-converting enzyme (ACE) inhibitor was approved in 1981, under the name Capoten® (Bristol-Myers Squibb, BMS, New York, NY, USA), for the treatment of cardiovascular diseases." (PMID 36499761, 2022). "The biological impact of the presence of deletion polymorphism of ACE in individuals with COVID-19 infection provides a significant rationale for serious consideration of short-term use of ACE-I and/or ARBs in patients without underlying issues with blood pressure or cardiovascular disorder." (PMID 32901433, 2021). "The angiotensin-converting enzyme (ACE) plays a central role in the RAAS, which is involved in the pathogenesis of cardiovascular diseases." (PMID 33925539, 2021). "Substantial evidence is needed to guide decision-making on the use of ACE inhibitors and ARBs in such patients, until then we need to base on the available data that place RAS inhibitors among the safe choices for cardiovascular diseases." (PMID 32850989, 2020).
cardiovascular disease (continued). "sACE, hereafter referred to simply as ACE, has been extensively studied, because of its crucial role in the homeostasis of renin-angiotensin-aldosterone (RAAS) system and in cardiovascular diseases." (PMID 33195436, 2020). "Angiotensin converting enzyme (ACE) inhibitors, including captopril, enalapril, and lisinopril, are mainly used in the treatment of cardiovascular diseases." (PMID 31590451, 2019). "The fact that 20-HETE, as a potent inducer of ACE, modulates the RAS activity and thus contributes in the pathophysiology of cardiovascular diseases is now well recognized." (PMID 30054426, 2018). "The angiotensin-converting enzyme (ACE), a member of the renin-angiotensin system (RAS) has been investigated extensively as a key gene for cardiovascular disease (CVD)." (PMID 25170764, 2014). "Moreover, 20-HETE acts as both a mediator and an amplifier of Ang II’s biological functions by enhancing ACE activity and AT1 receptor expression, thereby creating a positive feedback loop that drives cardiovascular disease progression." (PMID 39825084, 2025). "However, in our study, the lack of association with established cardiovascular disease may be due to the presence of multiple overlapping risk factors, medication effects (e.g., statins and ACE inhibitors), and the chronicity of disease, which could obscure biomarker differences." (PMID 41155371, 2025). "Tissue ACE, rather than circulating ACE, is increasingly recognized as a critical therapeutic target in managing cardiovascular diseases." (PMID 40149635, 2025). "Similarly, angiotensin-converting enzyme (ACE)-inhibitors and Ang II receptor blockers (ARBs) have been proposed, and are already widely deployed for the treatment of other cardiovascular diseases." (PMID 37799778, 2023). "Medicines and commodities related to cardiovascular disease include metformin, aspirin, and beta-blockers (available at all BHUs), and ACE inhibitors and calcium channel blockers were not available at any of the BHUs." (PMID 36969638, 2023). "Cardiovascular disease medications such as aspirin (ASP), statins like atorvastatin (ATR), and blood pressure-lowering drugs including ACE inhibitors like ramipril (RAM) have been included in the World Health Organization (WHO) Essential Medicines List (EML) for many years." (PMID 36922850, 2023). "As a sensitivity analysis, we evaluated treatment effect heterogeneity of thiazide or thiazide-like diuretics compared to ACE inhibitors in patients with or without prior cardiovascular disease." (PMID 36991144, 2023). "Given the success of these RAS inhibitors (the angiotensin converting enzyme (ACE) inhibitors and angiotensin II receptor blockers (ARBs)) in treating cardiovascular diseases, the decision to discontinue their use, or not, should not be made lightly." (PMID 34198530, 2021). "Therefore, ACE inhibitors (ACEIs) and AT1 receptor blockers (ARBs) are applied for the treatment of cardiovascular diseases via blocking and/or reducing the adverse effects of Ang II." (PMID 33396184, 2020). "Similarly, a number of groups have demonstrated the dominant expression pattern of ACE and AT1 receptor over ACE2 and Mas1 receptor in pulmonary and cardiovascular diseases." (PMID 29731719, 2018). "ACE, being a key regulator of the renin-angiotensin-aldosterone system (RAAS), is if inhibited with flavonoids, can easily manage the blood pressure and related cardiovascular disorders." (PMID 30581531, 2018). "For example, EGCG can inhibit the angiotensin-converting enzyme (ACE) activity through oxidation into an electrophilic quinone, which may be related to the treatment of cardiovascular diseases." (PMID 28884125, 2017). "Angiotensin-I converting enzyme (ACE) is a zinc dipeptidylcarboxypeptidase with two active domains and plays a key role in the regulation of blood pressure and electrolyte homeostasis, making it the principal target in the treatment of cardiovascular disease." (PMID 26403559, 2015).
cardiovascular disease (continued). "Many studies have demonstrated that renin-angiotensin system (RAS) inhibitors such as angiotensin receptor blockers (ARBs) and angiotensin converting enzyme inhibitors (ACE-Is) slow the rate of progression of DKD and reduce the incidence of cardiovascular disease and ESRD." (PMID 26362195, 2015). "Several recent reviews evaluating the potential role of an increased ACE expression in cardiovascular disease concluded that not the expression (and genotype), but the actual ACE activity is important." (PMID 24690767, 2014). "An other mutation that was accompanied by a 13-fold elevation of the serum ACE concentration was also without increased occurrence of cardiovascular disease." (PMID 24690767, 2014). "In addition, it was assumed that genetic variations that increase the expression or activity of ACE and ACE2 might contribute to cardiovascular disease and SARS-CoV-2 infection." (PMID 37667339, 2023). "Polymorphic loci of four genes whose products are involved in blood pressure control (ACE, BDKRB2, NOS3 and PPARGC1A) can be used in martial arts not only to determine predisposition to cardiovascular disease but also to predispose to the development of speed and power qualities and endurance." (PMID 36140844, 2022). "There is evidence of association of AGTR1 1166 A>C and ACE I/D polymorphisms with CKD and cardiovascular diseases, their roles in non-BP dipping at night, and nocturnal hypertension, but this remain unclear among African blacks." (PMID 31951214, 2020). "In view that ACE over-activation plays an important role in the pathogenesis of cardiovascular disease, as far as we know there are no reports whether the effects of FXST are associated with the inhibition of ACE." (PMID 26019516, 2014). "Using a multidisciplinary strategy, C. pyrenoidosa protein was investigated as a source of peptides active against ACE and DPP-IV targets, in line with the preclinical and clinical evidences suggesting that the consumption of C. pyrenoidosa may be useful for the prevention of cardiovascular disease." (PMID 34066103, 2021). "Though structurally similar, ACE and ACE2 have different functions, and hence, the action of ACE2 is not altered by ACE inhibitors that are used in cardiovascular disorders." (PMID 35153624, 2022). "Therefore, the ACE or AT1R blockers did not necessarily upregulate ACE2 expression in the lungs, and there was not enough reasons to stop taking ACE or AT1R inhibitors for SARS-CoV-2 infected patients with cardiovascular diseases." (PMID 33396184, 2020).
renal disease (345 papers, 2005 to 2026). "For T2DM patients with albuminuria, the AACE guidelines suggest using an angiotensin receptor blocker (ARB) or an ACE inhibitor to reduce the risk of renal disease." (PMID 40149950, 2025). "ACE inhibitors and angiotensin II receptor blockers (ARBs) have demonstrated the potential to reduce the severity of proteinuria and the risk of renal disease progression." (PMID 38254839, 2024). "Ìn any case, the genetic variation in ACE level has been, quickly after its discovery, associated with susceptibility to and prognosis of cardiovascular and renal diseases." (PMID 31316987, 2019). "On the opposite, genetically high ACE level is associated with increased risk of developing ischemic and diabetic cardiac or renal diseases and worsened prognosis of these diseases." (PMID 31316987, 2019). "Kidney disease secondary to subtotal nephrectomy (STNx) is associated with increased kidney ACE and Ang II, and, depletion of kidney ACE2 activity in both acute and chronic STNx." (PMID 25786223, 2015). "Nearly, all children with chronic proteinuric disorders receive an ACE inhibitor or an angiotensin II receptor blocker as adjunctive synergistic drugs aimed at averting progressive renal injury caused by the underlying renal disorder." (PMID 26793696, 2015). "Pediatric studies have found the insertion/deletion (I/D) polymorphism of the angiotensin-converting enzyme (ACE) gene to be associated with renal disease progression." (PMID 24883149, 2014). "In type 1 diabetic patients with microalbuminuria, ACE inhibitors reduce the risk of progression to overt nephropathy." (PMID 28197454, 2014). "The degree of urine albumin/protein is associated with the progression of kidney disease via the activation of tubular angiotensin-converting enzyme (ACE) inhibitors or inflammatory pathways." (PMID 23390421, 2013). "Recently, strong evidence has accumulated for a pathophysiological association between lung and kidney diseases and the ACE I/D polymorphism, which is correlated with circulating and cellular ACE levels." (PMID 22938636, 2012). "ACE gene polymorphism appeared to be an important genetic determinant in causation and progression of renal diseases and DD genotype was found to be significantly associated with advanced ESRD in children." (PMID 21859496, 2011). "Conclusively, ACE gene polymorphism appears to be an important genetic determinant in causation and progression of renal diseases and ACE DD genotype was found to be strongly associated with ESRD among north Indians." (PMID 17042963, 2006). "Overall findings were demarcating that D allele of ACE gene confers a high risk of developing renal diseases (OR = 3.36) and this association was highly compounded when D allele was present in homozygous state (OR = 5.74)." (PMID 17042963, 2006). "The data presented in this study is the first report from north India regarding the role of genetic variants of ACE gene in causation and progression of renal diseases." (PMID 17042963, 2006). "Presence (insertion-I) or absence (deletion -D) of a 287 bp fragment in the 16th intron of ACE gene has been linked to high prevalence of renal disorders among hypertensives and has been studied extensively." (PMID 17042963, 2006). "Although the association between the ACE I/D polymorphism and kidney diseases has been extensively researched, there was still obviously controversy about whether the DD genotype and/or D allele increase the renal scar susceptibility in VUR." (PMID 27506878, 2016). "Other factors relevant to the ethnic variance in the outcome may be genes related to progression of renal disease, such as ACE polymorphisms." (PMID 27022425, 2015). "ACE gene polymorphism has been investigated as one of the genetic factors that may affect the progression of a variety of renal diseases (for example, diabetic nephropathy, ESRD, IgA nephropathy)." (PMID 24883149, 2014).